PGR (progesterone receptor)
Diseases named in the same sentence as PGR in open-access papers (continued):
Sharing a sentence is not in itself a finding about the gene and the disease.
tumor (continued). "For our analysis, we select the 10 most differentially expressed genes between ‘pathologic complete response’ (34 patients) and ‘residual disease’ (99 patients), and the categorical variables estrogen receptor status, progesterone receptor status, tumor grade and molecular subclass." (PMID 29182671, 2017). "Additionally, ER+PgR+ patients, receiving hormonal therapy, have the advantage of avoiding a tumor relapse leading to a good long-term survival." (PMID 28173783, 2017). "Age, tumor size, number of involved LN, stage of disease, progesterone receptor status and human epidermal receptor are important prognosis factors at diagnosis and, in addition, loco-regional metastasis is an important intermediate prognosis factor of unadjusted OS." (PMID 27061995, 2016). "However, in the same patient group, 42.7 % of PgR+ primary tumour patients had PgR− metastases, whilst 16.0 % of PgR− primary tumour patients had PgR+ metastases, indicating a greater loss than gain of PgR expression in metastatic tissue." (PMID 27189371, 2016). "A number of factors have been shown to impact the response to DOX-based chemotherapy, including tumor stage, grade, the number of involved lymph nodes, and expression levels of estrogen receptor (ER), progesterone receptor (PR), and human epidermal growth factor receptor 2 (Her2)." (PMID 28036387, 2016). "Immunohistochemically, tumor cells usually show positive reactivity for neuroendocrine markers, including synaptophysin and chromogranin A. In addition, these tumors generally show positive reactivity for ER and PgR." (PMID 28105053, 2016). "In East Asian women, tumor heterogeneity was observed for rs2288378 (pTH = 0.04), in which a decreased risk of ER+ and/or PgR+/HER2− tumors, but not other tumor subtypes, was noted." (PMID 27376028, 2016). "Multivariate analysis determined that significant risk factors for outliers of ΔKi-67 were tumor size >1 cm, negative progesterone receptor (PR) expression, grade III cancer, and age ≤35 years." (PMID 26954364, 2016). "Furthermore, the percentage of PgR-positive tumor cells was as follows: 10–49 % in 127 tumors, 50–74 % in 119 tumors, and ≥75 % in 174 tumors." (PMID 27722840, 2016). "Therefore, our finding that patients with a tumor containing both ER and PgR did benefit from tamoxifen therapy seems reasonable." (PMID 27722840, 2016). "Bcl-2 expression was lost in 70 % of the most aggressive triple-negative BC cases, i.e. those lacking ERα, PgR and Her-2, and was significantly associated with high proliferation, tumor progression and increased risk of death and recurrence." (PMID 27538498, 2016). "For ER, we observed a clear reduction in such risk beyond 50% of tumor cells staining positively, whereas no such effect was seen for increasing PgR expression." (PMID 26910921, 2016). "We could not show any benefit from tamoxifen among patients with 1–9 % PgR-positive tumor cells (HR = 1.11, 95 % CI 0.38–3.24, p = 0.84)." (PMID 27722840, 2016). "Specifically, we recorded age, tumor size, nodal status, treatment type, pattern of relapse, second primary incidence, outcome (disease-free survival and overall survival), and biological features (estrogen receptor [ER], progesterone receptor [PgR], tumor grade, proliferation and c-erbB2 status)." (PMID 27899083, 2016). "Since the mid-1970s, pathological analysis of breast tumours, usually via IHC staining, has been used to determine the ER and progesterone receptor (PR) status of the tumor, with both markers having the ability to indicate the likelihood of recurrence and response to endocrine therapies." (PMID 25906750, 2015).
tumor (continued). "In Luminal-B patients with residual tumor after NCT, PgR loss was also independently correlated with poor relapse-free survival (P = 0.017; HR = 0.430; PgR- as a reference) and overall survival (P = 0.013; HR = 0.355; PgR- as a reference)." (PMID 26053183, 2015). "All nine patients had moderate to strong (grade 2–3) ER and PgR positive tumours." (PMID 25810898, 2015). "While we observed some intriguing associations among the underweight, including lower expression of ESR1 and PGR and being more likely to have a Basal-like tumor, we were limited by the small number of underweight women in our cohort (n = 13) to draw any definitive conclusions about this subgroup." (PMID 25884832, 2015). "Moreover, there was an association between the clusters and immunohistochemically (IHC) determined ERα (p = 4.1E-14) and PGR (p = 1.4E-12) status, with the better prognosis group (cluster 2) being enriched in ERα and PGR positive tumours." (PMID 26280373, 2015). "Specifically, intraocular biopsy may identify Her2/neu-positive patients that may benefit from adjuvant anti-Her2/neu therapy and estrogen or progesterone receptor-positive tumor cells that would respond to endocrine therapy administration." (PMID 26078956, 2015). "Compared to Luminal A tumours, Luminal B tumours are characterized by higher expression of proliferation/ cell cycle-related genes and lower expression of several luminal-related genes such as the progesterone receptor (PR)." (PMID 25932042, 2015). "However, univariable Cox regression analyses of disease-free survival showed a prognostic significance for the variables tumor grade, progesterone receptor status, clinical tumor size, and lymph node status." (PMID 26715527, 2015). "The frozen section histology showed an intraductal carcinoma of high grade with 2 focus, 3mm and 1mm corresponding to Infiltrating left breast carcinoma, grade II tumor of Scarff and Bloom, estrogen and progesterone receptor positive: it wasa multifocal cancer (SBRII, 21 N + / 26, RH +, low Ki 67)." (PMID 26664526, 2015). "Paired paraffin embedded pre- and post-statin treatment tumor samples were analyzed using immunohistochemistry for the expression of estrogen receptor (ER), progesterone receptor (PR), human epidermal growth factor receptor 2 (HER2), and the cell cycle regulators cyclin D1 and p27." (PMID 25925673, 2015). "As a consequence we sought to evaluate the expression of PGR in both tumor cells derived from epithelia (TE) and tumor stromal cells (TS) in malignant prostatectomy specimens and found the PGR density level in both TE and TS to be associated with PCa progression." (PMID 25723513, 2015). "Finally, 24 (12 %) tumours were triple-negative (ER-, PgR-, Her-2-) and 18 had Her2 over-expression (9 %)." (PMID 26238442, 2015). "Patients with ER+/PgR-/HER2-/ Ki-67 <20% tumours were once classified as luminal A patients who may only require endocrine therapy." (PMID 25938238, 2015). "A lack of progesterone receptor (PgR) expression in oestrogen receptor-positive (ER+) tumours is associated with worse survival." (PMID 25938238, 2015). "Emerging evidence indicates a correlation between that EMT marker expression and poor prognosis, while histopathologic changes in the EMT are associated with a high tumor grade, high mitotic index, and negative estrogen/progesterone-receptor status." (PMID 26536657, 2015). "On the other hand, recent studies based on next-generation sequencing have shed new light on tumor heterogeneity, reinforcing the hypothesis that variation in ER, PgR and HER2 status may actually reflect clonal genome evolution." (PMID 25032257, 2014). "Other factors may include population differences that vary by ethnicity, family history, menopausal status and tumor status of estrogen receptor (ER), progesterone receptor (PR), or human epidermal growth factor receptor 2 (HER2)." (PMID 24481062, 2014).
tumor (continued). "Furthermore, a significant decrease in the proliferation index (percentage of Ki67-labelled cells) was observed in progesterone-receptor positive and isoform-A positive tumours in aglepristone-treated dogs." (PMID 25515784, 2014). "Crossing of WAP-T1 mice with conditional progesterone receptor knock-out mice would be an interesting approach to investigate this hypothesis by testing for the requirement of this hormone receptor for tumor formation." (PMID 25019062, 2014). "We showed that FLC expression is associated with an aggressive tumor trait, particularly those with a triple-negative (estrogen receptor, progesterone receptor and HER2 negative) basal-like phenotype." (PMID 24931643, 2014). "On the other hand, the same ER+PgR− phenotype among the three tumor types with positive steroid receptors showed slower tissue invasion than the ER+PgR+ phenotype of the same tumor type (progression rate differences by 38% for Luminal A, 46% for Luminal B1 and 67% for Luminal B2 with Ki67 > 14%)." (PMID 24917206, 2014). "In three tumor types with positive steroid receptors the ER+PgR− phenotype showed slower IDC transition than the ER+PgR+ phenotype of the same tumor type (difference in progression rate was 38% for Luminal A, 46% for Luminal B1 and 67% for Luminal B2 with Ki67 > 14%)." (PMID 24917206, 2014). "Thus, there exists the potential for alterations in tumor characteristics, in particular predictive biomarkers such as ER, PgR and HER2." (PMID 24670368, 2014). "Despite these remarkable achievements, in general, clinicians still rely on traditional clinicopathologic features and readily available tumor markers such as estrogen receptor (ER), progesterone receptor (PR), and human epidermal growth factor receptor 2 (HER2)." (PMID 24955090, 2014). "Progesterone receptor (PR) negative expression was associated with higher tumor grade (p<.001) and higher Ki-67 index (p = .010)." (PMID 25170613, 2014). "However, since MCF-7-miR-155 cell line maintained an ERα+ phenotype with altered ERα signaling (evident through loss of PgR and high levels of TFF1), we next sough to determine the correlation between Rictor and PgR in a luminal B tumor subtype." (PMID 25283550, 2014). "Conventional prognostic and predictive factors include disease stage (tumour size, nodal status and presence of distant metastases), expression of oestrogen and progesterone receptors (ER and PgR, respectively), immunohistochemical/molecular status of HER-2, and Ki-67 expression." (PMID 23420497, 2013). "In the Cox’s proportional hazards model, which included age, menopausal status, tumor size, nodal status, nuclear grade, ER, PgR, HER2 and Ki67, Aurora A mRNA expression proved to be a significant prognostic univariate parameter (P = 0.006) and multivariate factor (P = 0.027) for RFS." (PMID 23627634, 2013). "We further evaluated whether tumor size, ER, PgR, HER2, and grade status had an effect on Ki67 performance between CNB and OEB." (PMID 23957561, 2013). "We studied the expression of AP-1 members at the mRNA level in 72 primary breast tumors and 37 adjacent non-tumor tissues and evaluated its correlation with clinicopathological parameters including estrogen receptor (ER), progesterone receptor (PR) and HER2/neu status." (PMID 24073962, 2013). "Further, while markers such as HER2 are quite homogeneously expressed across a tumour, ER and, particularly, PgR may be more heterogeneous." (PMID 23972025, 2013). "Another reason could be more heterogeneous distribution within the tumor for PgR compared with ER detection." (PMID 23957561, 2013).
tumor (continued). "It is tempting to speculate that a coordinated expression of PgR and cytoplasmic growth signalling factors including S6K2/4EBP1 may facilitate the proliferative and oncogenic role of PgR, promoting tumour progression and therapy resistance." (PMID 24131622, 2013). "Initial models included age (greater than 50), surgery, left or right breast, smoking status, collagen vascular disease, axillary dissection, tumor grade, pathologic T stage, estrogen receptor status, progesterone receptor status, Her2neu receptor status, and adjuvant hormone therapy treatment." (PMID 24416595, 2013). "On immunostaining, the tumor was positive for progesterone receptor, CD56, cytokeratin and CD10." (PMID 23760027, 2013). "The glycosylation dependent staining of GdA is tumour specific and correlates with the peptide-specific Gd staining though neither of the two is associated with estrogen receptor, progesterone receptor or clinic-pathological features." (PMID 24377825, 2013). "Screen detected tumours were more likely to express ER and/or PgR and to show a lower Ki67 index." (PMID 23305429, 2013). "In addition, the tumor exhibited a TN phenotype, in agreement with four out of the five previous reports of ACCs of the breast for which the results of ER, PgR and HER2 stains were available." (PMID 23374397, 2013). "Breast-feeding duration, but not milk production, was associated with ER and PgR status but not with other tumor characteristics." (PMID 23853760, 2013). "Interestingly, however, we observed a significant correlation between a decreased ezrin expression (BVS 0, 1, 2 versus BVS 3) and a positive PgR status in the tumour blood vessels (P = 0.028)." (PMID 23420497, 2013). "PR-negative neoplasms generally have poor prognosis than progesterone receptor-positive neoplasms." (PMID 23738123, 2012). "Of the five clinical variables available (histologic grade, ER-status, PgR-status, age, lymph node-status and tumor size) after backward elimination only lymph node-status and tumor size remained significant in the multivariate Cox models with proliferation and stromal-decorin or stromal-laminin." (PMID 22719844, 2012). "CD151 overexpression was found to be significantly associated with larger tumour size, higher nodal stage, advanced stage, absence of oestrogen receptor and progesterone receptor, and human epidermal growth factor receptor 2 overexpression." (PMID 22294188, 2012). "A study in 574 node-negative breast cancer patients showed that high VEGFA levels in tumor tissue were associated with larger tumor size, older age, and negative progesterone receptor (PR)." (PMID 23203097, 2012). "At univariate analysis, pathological tumor size, nodal status, histological grade, lymphangio invasion, progesterone receptor status, molecular subtype, type of surgery and adjuvant chemotherapy were significantly associated with overall and distant metastasis free survival." (PMID 21699739, 2011). "A comparison of FGFR2 staining with oestrogen and progesterone receptor status of tumours." (PMID 21418638, 2011). "To confirm part of our hypothesis, we focused on female-specific factors and initially evaluated tumor cells immunohistochemically using anti-estrogen and progesterone receptor antibodies." (PMID 21599949, 2011).
tumor (continued). "Furthermore, the multivariate analysis revealed that the status of distant metastasis at recurrence, Ki-67 at primary tumor, and PgR at recurrence were all independent factors." (PMID 22004841, 2011). "Furthermore, 48.2% had oestrogen-receptor-positive, 50.3% had progesterone-receptor-positive and 34.8% had C-erb B2-positive tumours." (PMID 21496310, 2011). "Interestingly, this was also evident in the protein staining for progesterone receptor (which was positive and decreased with treatment in both tumours) and Ki67 (mean value before treatment 12.3 and 16.6 after 14 days treatment)." (PMID 20646288, 2010). "In addition to the ability of hMSCs to induce hormone-independent MCF-7 tumourigenesis, we have also demonstrated an increase in progesterone receptor expression in MCF-7-hMSC derived tumours indicative of enhanced oestrogen receptor signalling." (PMID 21087507, 2010). "At this time, the subtype classifications most often used in clinical settings are based on the commonly measured tumor markers estrogen receptor (ER), progesterone receptor (PR), and HER2/neu (HER2), which offer imperfect but practical surrogates for genomic profiling." (PMID 21092082, 2010). "Building upon our previous observation of a hormone-independent phenotype in MCF-7 cells induced by hMSCs in vivo as well as increased progesterone receptor (PgR) expression of MCF-7 + hMSC derived tumours, we examined the involvement of ER signalling in the hMSC-MCF-7 cell interaction." (PMID 21087507, 2010). "One reasonable tumor marker is the estrogen regulated progesterone receptor (PgR)." (PMID 20550710, 2010). "Conventional markers for prognostication or treatment prediction or both include tumor size and lymph-node involvement, histologic grade, estrogen (ER) and progesterone receptor (PgR) expression, as well as human epidermal growth factor receptor 2 (HER2, HER2/neu, ERBB2) amplification status." (PMID 20576095, 2010). "Additionally, all seven tumours in this group which were PgR-positive displayed a reduction in staining intensity and score with treatment." (PMID 20646288, 2010). "Tissue sections cut from formalin-fixed paraffin-embedded blocks from biopsy specimens and postoperative tumor tissues were stained for the presence of estrogen receptor (ER), progesterone receptor (PgR), HER-2 (human epidermal growth factor receptor-2), and MIB-1(Ki-67)." (PMID 19845944, 2009). "In addition, we analyzed the correlation between the polymorphisms of B7-H4 gene and a series of clinicopathologic features, including lymph node metastasis, tumor size, and the statuses of estrogen receptor (ER) and progesterone receptor (PR)." (PMID 19903360, 2009). "To avoid epigenetic variations due to age, reproductive state and/or cancer stage, we pooled together, whenever possible, DNA of normal breast tissues derived from comparable donors (same age frame, tumor stage, estrogen receptor/progesterone receptor status, and so forth)." (PMID 19250546, 2009). "Some researchers suggested that immunohistochemically triple negative tumours (ER, PgR, and HER 2-negativity) could reliably be defined as basal-like tumours, making these two subgroups synonymous." (PMID 19695088, 2009). "A pCR rate below 4% was found in patients with ER-positive or PgR-positive tumours, normal bcl-2 status, low and medium proliferation activity, grade I/II differentiation, no clinical response after two cycles of chemotherapy, or positive clinical nodal status." (PMID 18380893, 2008).